TRAV8-1 (T cell receptor alpha variable 8-1)
Description:
V region of the variable domain of T cell receptor (TR) alpha chain that participates in the antigen recognition. Alpha-beta T cell receptors are antigen specific receptors which are essential to the immune response and are present on the cell surface of T lymphocytes. Recognize peptide-major histocompatibility (MH) (pMH) complexes that are displayed by antigen presenting cells (APC), a prerequisite for efficient T cell adaptive immunity against pathogens. Binding of alpha-beta TR to pMH complex initiates TR-CD3 clustering on the cell surface and intracellular activation of LCK that phosphorylates the ITAM motifs of CD3G, CD3D, CD3E and CD247 enabling the recruitment of ZAP70. In turn ZAP70 phosphorylates LAT, which recruits numerous signaling molecules to form the LAT signalosome. The LAT signalosome propagates signal branching to three major signaling pathways, the calcium, the mitogen-activated protein kinase (MAPK) kinase and the nuclear factor NF-kappa-B (NF-kB) pathways, leading to the mobilization of transcription factors that are critical for gene expression and essential for T cell growth and differentiation. The T cell repertoire is generated in the thymus, by V-(D)-J rearrangement. This repertoire is then shaped by intrathymic selection events to generate a peripheral T cell pool of self-MH restricted, non-autoaggressive T cells. Post-thymic interaction of alpha-beta TR with the pMH complexes shapes TR structural and functional avidity.
Synonyms: TCRAV1S1; TCRAV8S1; TRAV81
Gene: T-cell receptor variable (V) gene on chromosome 14 (21,797,287 to 21,797,886, forward strand). Ensembl gene ENSG00000211782.
Subcellular location: Cell membrane
Gene Ontology:
Biological process: adaptive immune response
Cellular component: immunoglobulin complex; plasma membrane
Homologues: Orthologues: mouse Trav9-4 (69% identical), mouse Trav9d-3 (67% identical), mouse Trav9n-3 (67% identical), mouse Trav9-2 (66% identical), mouse Trav9d-2 (65% identical), mouse Trav9n-2 (65% identical), mouse Trav9n-4 (65% identical), mouse Trav9d-4 (60% identical), mouse Trav9-1 (59% identical), mouse Trav9d-1 (58% identical). Paralogues in human: TRAV8-3 (74% identical), TRAV8-4 (64% identical), TRAV8-6 (64% identical), TRAV8-2 (60% identical), TRAV8-7 (60% identical), TRAV3 (54% identical), TRAV16 (48% identical).
Diseases named in the same sentence as TRAV8-1 in open-access papers:
TRAV8-1 is named in the same sentence as 2 diseases in open-access papers, as found by Europe PMC text mining. Sharing a sentence is not in itself a finding about the gene and the disease. The quoted sentences say what the papers report.
Sepsis (1 paper, 2024). Sepsis is defined as life-threatening organ dysfunction caused by a dysregulated host response to infection. "In addition, TRAV27 was over-represented, while TRAV8-1 and TRAJ37 were down-regulated in the E-SEP group compared to the Y-SEP group, which might indicate abnormalities in TCR repertoires in elderly patients with sepsis." (PMID 38909272, 2024).
TRAV8-1 also shares sentences with these, for which no sentence is quoted: COVID-19 (1 paper).